EGFR (epidermal growth factor receptor)
Diseases named in the same sentence as EGFR in open-access papers (continued):
Sharing a sentence is not in itself a finding about the gene and the disease.
breast carcinoma (continued). "As part of the experimental validation, EGFR detection was benchmarked against a melanoma line lacking EGFR expression (MM074, negative control) and a breast cancer line with high EGFR expression (MDA-MB-231, positive control), confirming the specificity of the detection method (data not shown)." (PMID 40994521, 2025). "The activation of the AKT signaling pathway is also necessary for HCMV entry, as demonstrated in EGFR-positive MB468 breast cancer cells, where HCMV entry triggered PI3K pathway activation, a response absent in EGFR-negative MB453 cells unless EGFR was ectopically expressed." (PMID 40002177, 2025). "EGF1 and EGFR were negatively regulated with BMI and IR in adipose tissue, whilst, in patients with bipolar disorder, BMI did not affect EGF1 levels; however, in breast cancer patients, there is a positive correlation between BMI and EGFR2." (PMID 40072105, 2025). "Breast cancer, a prevalent global health concern, has sparked extensive research efforts, particularly focusing on triple negative breast cancer (TNBC), a subtype lacking estrogen receptor (ER), progesterone receptor, and epidermal growth factor receptor." (PMID 39021344, 2025). "As expected, both the 5-membered ring (D5DO) and 7-membered ring (D7DO) showed no biological activity in EGFR- and HER2-overexpressing breast cancer cells since they deviate structurally from the pharmacophore by having a three- and a five-carbon linker, respectively." (PMID 40867591, 2025). "αEGFR-EndoP125A, a fusion that targeted EGFR, was more effective than both EndoP125A and the parental anti-EGFR antibody cetuximab at inhibiting endothelial angiogenesis, triple-negative breast cancer (TNBC) vasculogenic mimicry, and breast cancer cell motility in vitro." (PMID 39594584, 2024). "Up to now, there are no data indicating the ability of CBG to reduce EGFR expression; however, some studies demonstrated that CBD and THC can reduce EGFR expression in A549, H460, and H1792 cells and suppress EGF/EGFR signaling pathways in breast cancer." (PMID 38396679, 2024). "The lack of effectiveness of these antibodies is likely attributed to the fact that they are designed to block the activity of the epidermal growth factor receptor (EGFR), which is overexpressed in some cancer cells, a characteristic not observed in TNBC breast cancer." (PMID 38067203, 2023). "However, in a breast cancer cell line MDA468, IFN-γ inhibited cell proliferation while reducing the number of available EGFR binding sites, without any change in the EGFR affinity." (PMID 37759950, 2023). "The EGFR inhibitor gefitinib presented a low clinical benefit rate (CBR) and virtually no tumor response in patients with advanced breast cancer (ABC), regardless of whether their tumors were hormone receptor positive or hormone receptor negative." (PMID 37228871, 2023). "Triple-negative breast cancer (TNBC), a breast cancer subtype characterized by lack of estrogen and progesterone receptor expression and absence of EGFR-2 (HER2/erbB2) overexpression, accounts for 15–20% of all breast cancers and most commonly affects young women under the age of 45." (PMID 38072918, 2023). "In vitro studies suggested that an EGFR blockade could increase sensibility to HER2-targeted agents; however, trials with the EGFR inhibitors gefitinib and cetuximab in patients with breast cancer failed to improve patients’ long-term outcomes." (PMID 36010990, 2022). "Neratinib and afatinib are irreversible molecular inhibitors of HER2, EGFR and HER 4 approved by the FDA to treat EGFR-positive non-small and squamous lung cancer and HER2 positive breast cancer, which both demonstrate a significant activity against primary HER@-amplified cell lines and xenografts." (PMID 35406423, 2022).
breast carcinoma (continued). "The selectivity of the proxTEMA results were confirmed by analyses of EGFR negative CHO-K1 cells, and of normal human fresh-frozen colon tissue expressing very low EGFR levels as well as of breast cancer tissue section characterized as 0+ according to HER2 protein staining." (PMID 36189884, 2022). "Notably, EGFR overexpression was mainly observed in triple-negative breast cancer (TNBC), a subtype of breast cancer with estrogen receptor-negative, progestogen receptor-negative, and HER2 negative, accounting for 45-70% of all TNBC patients." (PMID 35414783, 2022). "Apart from HER-2 receptors, the glycoprotein non-metastatic melanoma protein b (GpNMB), epidermal growth factor receptor (EGFR), and ephrin A2 (EphA2) receptors have also been exploited, with formulations targeted to these receptors evaluated in breast cancer patients with HER-2-positive tumors." (PMID 35267507, 2022). "To confirm the interaction between the two receptors under endogenous expression levels in the context of breast cancer, we chose SKBR3 cells that, compared to other breast cancer cell lines, express higher levels of HER2 and intermediate/lower levels of RANK and do not express EGFR." (PMID 33785053, 2021). "In another study, curcumin also inhibited the basal phosphorylation of Akt/PKB in breast cancer cells but not directly, suggesting that it could be due to the decrease in EGF-induced EGFR activation that was observed." (PMID 34867402, 2021). "Therefore, it is not surprising that defects in EGFR degradation are seen, for example, in cholangiocarcinoma RBE and breast cancer cells." (PMID 35127732, 2021). "Mammary carcinomas lacking the expression of ER, PR, and HER2 are known as Triple-negative breast cancers and are furtherly subclassified into basal-like carcinomas when expressing basal/myoepithelial markers: cytokeratins CK5/6, or CK14 and/or the EGFR." (PMID 33801360, 2021). "Our results suggest that EGFR and CDK7 combination therapy may be a novel treatment strategy for breast cancers, regardless of subtype." (PMID 32155786, 2020). "This signaling is ERBB2-specific and appears not to depend on ERBB2 heterodimers as in the context of the breast cancer cell line used here (expressing negligible ERBB4 levels), silencing of EGFR and ERBB3 does not impair the ERK-dependent AKT de-phosphorylation elicited by Abs." (PMID 33037285, 2020). "Among the recurrently amplified and deleted loci, we noted that canonical oncogenes, such as EGFR and HRAS, were recurrently amplified in CMTs; however, amplification of ERBB2 and MYC, which is common in human breast cancers, was not reflected in the GISTIC peaks of CMTs." (PMID 32680987, 2020). "Although the amount of breast cancer stem cells within SKBR3 cells might range up to five percent, the here described EGFR enriched cell population is not identical but might belong to the described SKBR3 stem cell population." (PMID 33260837, 2020). "Breast cancer cells lacking ALIX, a protein involved both in EGFR spatial regulation and in EV secretion, displayed an enhancement of EGFR activation, as well as an impairment in PD-L1+ EV release which conferred a more immunosuppressive phenotype to the tumour cells." (PMID 33302515, 2020). "Breast carcinomas with basal-like phenotypes have been parallelly described in the literature, and core basal phenotype has been described as a subset of triple negative breast cancers that are positive for CK5/6 and EGFR." (PMID 33218360, 2020). "EGFR altered cases unanticipatedly inversely correlated with proliferation factor expression in LUAD, Colon adenocarcinoma, and Cancer Cell Line Encyclopedia cell lines, but not in glioblastoma or breast cancer." (PMID 31857847, 2019).
breast carcinoma (continued). "AR expression in the primary breast cancers correlated with expression of p-HER2, EGFR, p-EGFR, p-IGFR, and p-ERK in patients who did not benefit from letrozole plus dasatinib (PFS ≤ 6 months), suggesting a potential interaction between AR and HER family receptors in letrozole/dasatinib resistance." (PMID 31667338, 2019). "Strikingly, the decreased invasiveness was re-increased by the transient transfection of the shRNA-resistant HDAC3wt plasmid, but not by rshHDAC3Y321/331, strongly confirming that EGFR–c-Src mediated HDAC3 phosphorylation at Y321 and 331 was crucial for the invasion of breast cancer cells." (PMID 31430896, 2019). "Later, Basal-like breast cancer (BLBC) was defined as estrogen receptor (ER) negative, human epidermal growth factor receptor 2 (Her-2) negative; epidermal growth factor receptor (EGFR, also known as Her-1) or/and Cytokeratin 5/6 (CK 5/6) positive." (PMID 31462314, 2019). "The second outcomes are clinicopathological parameters in breast cancer including the following items: histological grade; lymph node metastasis; The TNM classification of malignant tumors stage; the expression of HER-2, EGFR, estrogen receptor, PR, MKI67, cytokeratin 5/6." (PMID 30896652, 2019). "Although the EGFR-MAPK-PI3K pathway upregulates the expression, activity, and protein level of FOXC1, the how and why of FOXC1 being exclusively expressed in BLBC rather than in other breast-cancer molecular subtypes has yet to be answered." (PMID 29487724, 2018). "Furthermore, aplidin induced other kinases such as the epidermal growth factor receptor (EGFR), the non-receptor protein-tyrosine kinase Src, and the serine/threonine kinases JNK and p38 MAPK in the MDA-MB-231 breast cancer cells." (PMID 29558431, 2018). "FDA-approved mAbs such as rituximab (anti-CD20), trastuzumab (anti-HER2), and cetuximab (anti-HER1/anti-EGFR) used in lymphoma, breast cancer, head and neck, and colorectal carcinomas, respectively, not only block tumor cell signaling but also induce innate and adaptive antitumor immunity." (PMID 28674498, 2017). "Hence, we confirm previous studies in that EGFR (over)expression is not a feasible predictive marker for EGFR-targeted therapy, quite in contrast to what is seen for e.g. HER2-targeted therapy in breast cancers." (PMID 28199979, 2017). "Interestingly, we found that elevation of LINC00052 levels induce HER3 expression and signaling but not EGFR, HER2 or HER4 and exerts increased growth of breast cancer cells." (PMID 28036286, 2017). "Many breast cancers, particularly those that do not express estrogen receptor, progesterone receptor, or high levels of HER2 (i.e., triple negative breast cancer (TNBC)) have high levels of expression of EGFR." (PMID 26143491, 2015). "Even within breast cancer cell lines that do not over-express HER2, such as triple negative MDA-MB-231 cells, EGFR-induced signalling through PI3K/Akt is thought to be involved in mediating EMT, while several other studies implicate MEK1/2-ERK1/2 signalling as an important driver." (PMID 25975820, 2015). "From an immunohistochemical point of view basal-like breast cancers typically express basal cytokeratins such as CK5/6, CK17 as well as cadherin, and epidermal growth factor receptor (EGFR); however, there are no phenotypically patterns which “per se” allow us to define basal-like breast carcinoma." (PMID 26387133, 2015). "Some studies suggest that c-Met is a stronger prognostic indicator of poor prognosis than traditional markers such as Her2/neu and epidermal growth factor receptor (EGFR), whereas others show no statistically significant relation between c-Met and prognosis in breast cancer." (PMID 26047809, 2015). "Lapatinib (Tykerb, GW-572016), a dual tyrosine kinase inhibitor of epidermal growth factor receptor (EGFR) and HER2 receptors, has been used for advanced HER2-positive breast cancer patients who failed to chemotherapy or HER2-targeted therapy with monoclonal antibody trastuzumab." (PMID 24707474, 2014).
breast carcinoma (continued). "Although lapatinib, an FDA-approved small-molecule HER2 and epidermal growth factor receptor (EGFR) tyrosine kinase inhibitor (TKI), represents a significant therapeutic advancement in the treatment of HER2+ breast cancers, responses to lapatinib have not been durable." (PMID 24044505, 2013). "Expression of EGFR and HER2 was not significantly different between male and female breast cancer." (PMID 23308200, 2013). "However, there are no reports about the impacts of co-inhibition of EGFR and IGR-1R on radiosensitivity of breast cancer cells." (PMID 23777562, 2013). "MDA-MB-436 primary tumors were CK18 positive, EGFR positive, Her2 negative, demonstrating that the NSG MDA-MB-436 xenograft tumors also retained the MDA-MB-436 cell line expression pattern of key breast cancer markers." (PMID 23118918, 2012). "Furthermore, preferential phosphorylation of HER3, but not EGFR, was observed in HER2-amplified breast cancer tissues." (PMID 23198146, 2012). "However, the therapeutic effects of EGFR and mTOR inhibitors in combination have not yet been broadly assessed in HER2 overexpressing breast cancers with different TZ sensitivity." (PMID 21961653, 2011). "EPA did not modify EGFR expression in breast cancer cells; while EGF stimulation significantly increase EGFR phosphorylation to about 140%; co-treatment with EPA/EGF significantly inhibit EGFR activation down to about 40% compared to control non stimulated cells." (PMID 21569413, 2011). "Preclinical studies in breast cancer cell lines that overexpress HER2 show that combined EGFR and HER2 inhibition may be more effective than treatment with single agents, regardless of EGFR expression level." (PMID 16622439, 2006). "Although EGFR was suggested to be one of upstream regulators of PDK-1/AKT and Stat3 pathways, the role of EGFR activation plays in relation to PDK-1/AKT/mTOR/p70S6K/S6 cascade in breast cancers has not been firmly established." (PMID 16288304, 2005). "In breast cancer cells BT474 (ER and HER2 positive) and SKBR3 (ER negative, HER2 positive) exposed long-term to EGFR-targeted small molecules (gefitinib, erlotinib) and colon cancer cells SW48 exposed long-term to anti-EGFR monoclonal antibody cetuximab, the development of resistance was analyzed." (PMID 38606172, 2024). "This trial showed that the combination of lapatinib (an inhibitor of EGFR and HER2) with paclitaxel did not provide significant benefits to TNBC and HER2−progesterone receptor (PR) high patient groups but exhibited notable therapeutic advantages in other metastatic breast cancer cohorts." (PMID 39668367, 2024). "In breast cancer, Jeong and colleagues found that PMCA2 knockdown disrupted the interaction between HER2 and HSP90 and promoted the internalization and degradation of HER2, resulting in a reduction in the protein levels of p-EGFR, HER3, and p-HER3, but not EGFR." (PMID 35600399, 2022). "In addition, SHP-1 was found to inactivate signal transducers and activators of transcription 3 (STAT3) in HER2-overexpressing breast cancer cells (data not shown), thus indicating that the tumor-suppressive effects of SHP-1 cannot be fully compromised by EGFR/Ras/Erk/GSK3β pathway inactivation." (PMID 34591414, 2021). "In vitro, knocking down TGFA did not reduce breast cancer cell production of MCSF, but did reduce the expression of CCL2, leading the authors to conclude that breast cancer cell-derived TGFα induced autocrine EGFR signaling, leading to increased CCL2 and macrophage recruitment." (PMID 33069212, 2020). "Despite EGFR being highly expressed in a large proportion of TNBC patients, the employment of engineered monoclonal antibodies (mABs) against EGFR is not approved for the treatment of breast cancer, while it is approved for other types of cancer such as colorectal cancer." (PMID 29113326, 2017).
breast carcinoma (continued). "Moreover, non-malignant HFF cells that express wild-type EGFR were less sensitive to the apoptotic effects of PUVA, consistent with the notion that EGFR is not responsible for induction of apoptosis in PUVA-treated ErbB2+ breast cancer cells." (PMID 24551203, 2014). "However, in HER2+ breast cancer cells that have become resistant to lapatinib, HER3 phosphorylation can be regulated by EGFR-HER3 dimers, which were not responsive to inhibition by lapatinib or other EGFR TKIs." (PMID 24044505, 2013). "The involvement of the ErbB signaling pathway is not surprising – it is well-known that the ErbB protein family or epidermal growth factor receptor (EGFR) family, especially ErbB-2 (HER-2), is often over-expressed with aggressive clinical behavior and poor outcome in patients with breast cancer." (PMID 22346740, 2012). "In nude mice transplanted with human breast carcinoma, it was shown that rhEGF inhibited the growth of EGF receptor (EGFR)-positive MX-1 cells in a dose-dependent manner, whereas no changes were observed in the growth of cells of EGFR-negative MCF-7, Br-10 or T-61 after treatment with rhEGF." (PMID 19456848, 2009). "The breast cancer cell lines tested exhibit similar surface expression of the IGF-1 receptor, but the number of EGF receptors varied considerably, with MDA468 cells showing very high expression, MDA231 intermediate levels, SK-BR-3 low expression, and MCF-7 no significant presence of EGFR." (PMID 15987464, 2005). "Additionally, EGFR and HER2 interact with the nongenomic signalling pathways of ER; they regulate the expression of ERα isoforms and play major roles in the development of tamoxifen resistance in breast cancer by providing alternative pathways for cancer growth." (PMID 35454796, 2022). "Importantly, in a recent study, researchers found that in breast cancer cells with acquired letrozole resistance, the constitutive activation of the AKT/mTOR pathway could be blocked by PI3K and/or mTOR inhibitors, but not by EGFR/ErbB2 inhibitors." (PMID 25633049, 2015).